LINC01085 (long independently transcribed non-coding RNA 1085)
Synonyms: KLF17P2
Gene: Transcribed processed pseudogene on chromosome 4 (14,126,339 to 14,126,664, forward strand). Ensembl gene ENSG00000248698.
Diseases named in the same sentence as LINC01085 in open-access papers:
LINC01085 is named in the same sentence as 1 disease in open-access papers, as found by Europe PMC text mining. Sharing a sentence is not in itself a finding about the gene and the disease. The quoted sentences say what the papers report.
tumour (1 paper, 2025). "LINC01085, a tumour suppressor with potential immunotherapy relevance, was downregulated in both cell types." (PMID 40559957, 2025). "Notably, the marked activation of CYP1A1, CYP1B1, and SLC16A6, coupled with the downregulation of tumour suppressors such as LINC01085 and CBS, underscores the potential of PM2.5 to promote oxidative stress, carcinogenesis, and therapy resistance in a mutation-dependent manner." (PMID 40559957, 2025).